LINC02321 (long independently transcribed non-coding RNA 2321)
Gene: Long non-coding RNA gene on chromosome 14 (90,820,042 to 90,828,274, reverse strand). Ensembl gene ENSG00000258884.
Diseases named in the same sentence as LINC02321 in open-access papers:
LINC02321 is named in the same sentence as 1 disease in open-access papers, as found by Europe PMC text mining. Sharing a sentence is not in itself a finding about the gene and the disease. The quoted sentences say what the papers report.
cervical cancer (1 paper, 2024). A primary or metastatic malignant neoplasm involving the cervix. "Experimental studies have shown that LINC01833 and LINC02321 are also upregulated in cervical cancer, and interference with their expression through siRNA transfection significantly reduces cell proliferation and migration capabilities." (PMID 38609663, 2024). "We observed significant upregulation of LINC01833 and LINC02321 in cervical cancer cell lines indicating that LINC01833 and LINC02321 may be potential role in cervical cancer development." (PMID 38609663, 2024). "Furthermore, compared to the NC, the knockdown of LINC01833 and LINC02321 significantly decreased the migration capability of cervical cancer cells." (PMID 38609663, 2024).